DHRS12 (dehydrogenase/reductase 12)
Description:
Putative oxidoreductase.
Synonyms: SDR40C1; FLJ13639
Tractability: No criterion of Open Targets' tractability assessment is met for any kind of drug.
Gene: Protein-coding gene on chromosome 13 (51,767,520 to 51,804,187, reverse strand). Ensembl gene ENSG00000102796.
Subcellular location (Human Protein Atlas): Nucleoplasm; Golgi apparatus; Vesicles
Genetic constraint (gnomAD): Loss-of-function variants: 23 observed, 26.29 expected, observed/expected ratio (o/e) 0.87, 90% interval 0.63 to 1.24. The upper end of that interval is the gene's LOEUF score, 1.24, which puts it in group 5 of 6, group 1 being the genes least tolerant of losing a copy. Missense variants: 300 observed, 298.47 expected, observed/expected ratio (o/e) 1.01, 90% interval 0.91 to 1.11. Synonymous variants: 136 observed, 118.14 expected, observed/expected ratio (o/e) 1.15, 90% interval 1 to 1.33.
Homologues: Orthologues: chimpanzee DHRS12 (84% identical), macaque DHRS12 (79% identical). Paralogues in human: RDH11 (21% identical), RDH5 (21% identical), RDH12 (20% identical), HSD11B2 (20% identical), DHRS9 (19% identical), HSD17B2 (19% identical), RDH16 (19% identical), BDH1 (18% identical), HSD17B7 (18% identical), HSD17B13 (17% identical), HSD17B6 (17% identical), SDR9C7 (17% identical), and 13 more.
Diseases named in the same sentence as DHRS12 in open-access papers:
DHRS12 is named in the same sentence as 2 diseases in open-access papers, as found by Europe PMC text mining. Sharing a sentence is not in itself a finding about the gene and the disease. The quoted sentences say what the papers report.
osteosarcoma (1 paper, 2024). A usually aggressive malignant bone-forming mesenchymal neoplasm, predominantly affecting adolescents and young adults. "DHRS12 inhibits osteosarcoma proliferation and metastasis via the Wnt3a/β-catenin pathway." (PMID 38212774, 2024).
DHRS12 also shares sentences with these, for which no sentence is quoted: systemic lupus erythematosus (2 papers).